PLAAT4 (phospholipase A and acyltransferase 4)
Description:
Exhibits both phospholipase A1/2 and acyltransferase activities. Shows phospholipase A1 (PLA1) and A2 (PLA2), catalyzing the calcium-independent release of fatty acids from the sn-1 or sn-2 position of glycerophospholipids. For most substrates, PLA1 activity is much higher than PLA2 activity. Shows O-acyltransferase activity, catalyzing the transfer of a fatty acyl group from glycerophospholipid to the hydroxyl group of lysophospholipid. Shows N-acyltransferase activity, catalyzing the calcium-independent transfer of a fatty acyl group at the sn-1 position of phosphatidylcholine (PC) and other glycerophospholipids to the primary amine of phosphatidylethanolamine (PE), forming N-acylphosphatidylethanolamine (NAPE), which serves as precursor for N-acylethanolamines (NAEs).
Synonyms: HRSL4; RARRES3; RIG1; TIG3; HRASLS4; PLAAT-4; PLA1/2-3
Tractability: Small molecule: a high-quality ligand is known. Antibody: UniProt predicts a signal peptide or a membrane-spanning region. PROTAC: ubiquitination databases record sites on it; a small molecule that binds it is known.
Target class: Enzyme; Transferase
Gene: Protein-coding gene on chromosome 11 (63,529,451 to 63,548,808, forward strand). Ensembl gene ENSG00000133321.
Subcellular location: Membrane
Pathways (Reactome):
Metabolism: Acyl chain remodelling of PE
Gene Ontology:
Molecular function: acyltransferase activity, transferring groups other than amino-acyl groups; phospholipase A1 activity; phospholipase A2 activity; protein binding; acyltransferase activity
Biological process: N-acylphosphatidylethanolamine metabolic process; phospholipid metabolic process; negative regulation of cell population proliferation; phosphatidylethanolamine acyl-chain remodeling
Cellular component: cytoplasm; cytosol; membrane
Genetic constraint (gnomAD): Loss-of-function variants: 14 observed, 14.59 expected, observed/expected ratio (o/e) 0.96, 90% interval 0.63 to 1.5. The upper end of that interval is the gene's LOEUF score, 1.5, which puts it in group 6 of 6, group 1 being the genes least tolerant of losing a copy. Missense variants: 162 observed, 218.97 expected, observed/expected ratio (o/e) 0.74, 90% interval 0.65 to 0.84. Synonymous variants: 77 observed, 83.25 expected, observed/expected ratio (o/e) 0.92, 90% interval 0.77 to 1.12.
Homologues: Orthologues: chimpanzee PLAAT4 (99% identical), macaque PLAAT4 (70% identical), dog PLAAT4 (63% identical). Paralogues in human: PLAAT2 (48% identical), PLAAT3 (48% identical), PLAAT5 (45% identical), PLAAT1 (43% identical), LRAT (27% identical), LRATD2 (26% identical), LRATD1 (22% identical).
Diseases named in the same sentence as PLAAT4 in open-access papers:
PLAAT4 is named in the same sentence as 53 diseases in open-access papers, as found by Europe PMC text mining. Sharing a sentence is not in itself a finding about the gene and the disease. The quoted sentences say what the papers report.
breast carcinoma (15 papers, 2014 to 2025). "Additionally, activation of the Wnt/β-catenin and PI3K-AKT pathways plays a crucial role in PLAAT4-silenced breast cancer cells." (PMID 40777995, 2025).
hepatocellular carcinoma (6 papers, 2020 to 2025). A malignant tumor that arises from hepatocytes. "G9a is frequently overexpressed in hepatocellular carcinoma (HCC) and silences the tumor suppressor phospholipase A and acyltransferase 4 (RARRES3)." (PMID 35740522, 2022).
cervical cancer (3 papers, 2011 to 2023). A primary or metastatic malignant neoplasm involving the cervix. "PLAAT4 in HtTA cervical cancer cells was also shown to interact with the RAS, a plasma membrane-associated GTPase that regulates proliferation, differentiation and apoptosis by serving as binary switches." (PMID 37063830, 2023). "In cells overexpressing the tumor suppressor gene phospholipase A and acyltransferase 4 (PLAAT4), RPLPO levels are decreased suggesting that the ratio of RPLP0 to PLAAT4 is an important regulator of cervical cancer growth and development." (PMID 34873618, 2021). "For instance, it was suggested that PLAAT4 could form a protein complex with the ribosomal protein P0 (RPLP0) in HtTA cervical cancer cells." (PMID 37063830, 2023).
breast tumor (2 papers, 2014 to 2023). "In this regard, PLAAT4 is among the metastasis-associated gene signatures whose expression levels in primary breast tumors inversely correlate with the frequency of lung metastasis." (PMID 37063830, 2023). "Hence, PLAAT4 could also indirectly suppress the distant metastasis of breast tumor cells by down-regulating PSMB8/9/10 expression." (PMID 37063830, 2023).
parasite infection (2 papers, 2021 to 2023). "However, more recent findings have also identified PLAAT4 as a key anti-microbial effector enzyme acting downstream of interferon regulatory factor 1 (IRF1) and interferons (IFNs), favoring protection from virus and parasite infections." (PMID 37063830, 2023).
schizophrenia (2 papers, 2021 to 2023). A major psychotic disorder characterized by abnormalities in the perception or expression of reality. "We noticed four of the DEGs (PLD2, PLCB3, PLAAT4, RPS27) involved in these pathways were also differentially expressed in the brain of patients with schizophrenia." (PMID 34630179, 2021).
serous ovarian cancer (1 paper, 2025). "Clinical analyses revealed that BCL6 expression is significantly elevated in high-grade serous ovarian cancer (HGSOC) tissues compared with that in normal tissues, whereas PLAAT4 expression is reduced." (PMID 40777995, 2025).
tumor (42 papers, 2003 to 2025). "Next, we examined the association between PLAAT4 expression and patient clinicopathological data and found that low PLAAT4 expression was associated with advanced tumor stage." (PMID 40777995, 2025). "Since its discovery, over two decades of research have unveiled the molecular mechanisms underlying PLAAT4-mediated restriction of tumor development and progression." (PMID 37063830, 2023). "Interestingly, the expression of PLAAT4, a tumor suppressor associated with the PI3K-AKT pathway, was negatively correlated with the expression of BCL6." (PMID 40777995, 2025). "Besides being identified as a tumor suppressor, there is growing evidence suggesting that PLAAT4 also plays crucial roles in restricting tumor metastasis, the main cause of cancer-related death." (PMID 37063830, 2023). "Meanwhile, cells that co-overexpressed BCL6 and PLAAT4 showed similar rates of tumor growth as NS cells." (PMID 40777995, 2025). "IHC analysis of the respective tumor samples showed efficient suppression of PLAAT4 upon overexpression of BCL6, while the expression of p-AKT was significantly increased." (PMID 40777995, 2025). "Re-expression of PLAAT4 reversed the activation of the PI3K/AKT pathway in BCL6-overexpressing SKOV3 or COV504 cells, and PLAAT4 was found to play a tumor suppressor role in HGSOC cells." (PMID 40777995, 2025). "Compared with those with other FIGO stages of HGSOC, more patients with FIGO stage III/IV HGSOC had lower PLAAT4 expression in tumor cells." (PMID 40777995, 2025). "PLAAT4 expression was expressed in the cytoplasm of tumor cells (positive rate: 65.85%) at a lower level than in normal fallopian tube tissues." (PMID 40777995, 2025). "As a tumor suppressor, PLAAT4 can inhibit tumor progression through various pathways, with the PI3K-AKT pathway being one of the most significant mechanisms." (PMID 40777995, 2025). "PLAAT4 is a tumor suppressor induced by retinoids, and its high expression in cancer favors inhibiting the growth of cancer cells and promotes apoptosis." (PMID 38951569, 2024). "As for PLAAT4, whose another familiar name is RARRES3, it is commonly believed to function as a tumor suppressor and is related to tumor differentiation." (PMID 38462627, 2024). "Being originally identified as a tumor suppressor, it is somewhat surprising that PLAAT4 is also one of the common downstream targets of IRF1 and IFN signals." (PMID 37063830, 2023). "As our understanding of the tumorigenic process has grown significantly, many mechanistic aspects of the tumor-suppressing activity of PLAAT4 have become clear during the past two decades." (PMID 37063830, 2023). "As a member of the class II tumor suppressor gene family, PLAAT4 exhibits phospholipase A1/2 and acyltransferase activities with pleiotropic effects that profoundly affect host immunity against tumors and pathogens." (PMID 37063830, 2023). "As a class II tumor suppressor, PLAAT4 that is found abundantly in normal tissues has been noted to favor differentiation and apoptosis but inhibit cell proliferation and attenuates tumor growth." (PMID 37063830, 2023). "In addition, the effect of reducing tumor weight by downregulating CRABP2 was significantly restored after silencing PLAAT4." (PMID 40657374, 2025). "In addition, patients with HGSOC who presented with lower PLAAT4 expression in primary tumors had significantly poorer OS outcomes, indicating that PLAAT4 is a key tumor suppressor in HGSOC." (PMID 40777995, 2025). "Given that the crucial roles of PLAAT4 in tumor progression and lipid metabolism, we hypothesized that it plays a vital role in the oncogenic activity of CRABP2." (PMID 40657374, 2025).
tumor (continued). "Being shared by anti-tumor and anti-pathogen responses, pathogen-triggered PLAAT4 expression may also offer potential to suppress tumorigenesis and development." (PMID 37063830, 2023). "T cells were found to be localizing selectively around a distinct malignant duct located center-left of the tissue section, with attributed genes such as immune checkpoint costimulatory receptor CD28, as well as IFIT3, CCL5, and PLAAT4 implicating an active anti-tumor immune response." (PMID 36906603, 2023). "In this review, we summarize recent progress in understanding how PLAAT4 promotes tumor suppression and pathogen restriction, focusing on its biochemical properties and transcriptional regulation, and discuss potential mechanisms in tumor prevention and anti-pathogen defense." (PMID 37063830, 2023). "A ubiquitous presence of PLAAT4 and its effector functions in tumor suppression and pathogen restriction suggest it might represent a self-protecting mechanism." (PMID 37063830, 2023). "PSMB8 could be detected with a relatively high expression in various immune cells and tumor cells, and PLAAT4 showed a relatively high expression in CD4+ T cells, CD8+ T cells, NK cells, and proliferative T cells." (PMID 36072600, 2022). "To confirm whether the BCL6-PLAAT4 axis plays the same role in vivo as that in vitro, we established a subcutaneous transplantation tumor and abdominal metastasis model of the SKOV3 cells in nude mice following replenishment of either BCL6 gene or co-replenishment of both BCL6 and PLAAT4." (PMID 40777995, 2025). "In vivo, we established a subcutaneous transplantation tumor model and abdominal metastasis model in nude mice to verify the role of BCL6 and PLAAT4 in HGSOC progression." (PMID 40777995, 2025). "PLAAT4, also known as retinoic acid receptor responder 3 (RARRES3) or retinoid-inducible gene 1 (RIG-1), is characterized as a tumor suppressor and plays a role in the induction of type I interferon (IFN-1) and MHC-I expression." (PMID 36072600, 2022).
cancer (27 papers, 2003 to 2025). A tumor composed of atypical neoplastic, often pleomorphic cells that invade other tissues. "Apart from the membrane system, PLAAT4 also distributes at the centrosome in skin cancer cells, leading to pericentrosomal organelle accumulation which in turn drives cancer cell apoptosis." (PMID 37063830, 2023). "More recently, the anti-pathogen properties of PLAAT4 have come to light, expanding its focus from cancer biology to anti-pathogen defense mechanisms." (PMID 37063830, 2023). "Follow-up studies with epidermal squamous cancer cells suggested that PLAAT4 is also important for limiting cancer cell proliferation." (PMID 37063830, 2023). "Interestingly, PLAAT4 appears to inhibit proliferation and promote apoptosis via different mechanisms in other types of cancer cells." (PMID 37063830, 2023). "Understanding a comprehensive picture of PLAAT4 would open new avenues of PLAAT4 regulome that could impact biological events other than protection against cancers and pathogens." (PMID 37063830, 2023). "However, it should be noted that, while PLAAT4 promotes normal keratinocyte death via enhancing transglutaminase activity, the pericentrosomal localization of PLAAT4 in cancer cells drives organelle accumulation which in turn triggers caspase-dependent apoptosis." (PMID 37063830, 2023). "Notably, PLAAT4 in these cells is largely localized near the centrosome, and thus could inhibit centrosome separation during mitosis, leading to the induction of cancer cell apoptosis." (PMID 37063830, 2023). "PLAAT4 belongs to the lecithin retinol acyltransferase (LRAT) protein family and has been proposed to suppress cancer cell invasion and metastasis." (PMID 40657374, 2025). "Notably, PLAAT4 exhibits a time- and concentration-dependent expression pattern in response to ATRA, similar to IFNs that also play functional roles in anti-cancer immunity." (PMID 37063830, 2023). "For instance, it was demonstrated that the pro-apoptotic and anti-cancer activities of PLAAT4 are attributed primarily to the Golgi- rather than the endoplasmic reticulum-associated protein form." (PMID 37063830, 2023).
infection (8 papers, 2011 to 2023). The state of being infected such as from the introduction of a foreign agent such as serum, vaccine, antigenic substance or organism. "In summary, PLAAT4 research, while still in its infancy, has just begun to be emerged as an important field with relevance to host immunity to infection and disease progression." (PMID 37063830, 2023). "Since it has just begun to appreciate the roles for PLAAT4 in the restriction of tumors and pathogen infections, several important gaps have remained in terms of mechanistic understanding of its function." (PMID 37063830, 2023). "Although more investigations are required to answer above questions, further understanding of the molecular details of the PLAAT4 action would contribute to the development of more effective therapeutic approaches to treat tumors and pathogen infections." (PMID 37063830, 2023). "Thus, identifying the selectivity of PLAAT4 would reveal the type of cellular organelle membranes specifically targeted by different pathogens for productive infection." (PMID 37063830, 2023). "In this context, further studies are needed to dissect whether PLAAT4, especially its catalytic activity, can regulate mTOR-dependent autophagy and/or apoptosis to restrict pathogen infections." (PMID 37063830, 2023). "Because the absence of the important antiviral effector, PLAAT4, in rodents precluded use of a mouse infection model, we examined the impact of silencing CSNK2B expression on HAV replication in primary human hepatocytes (PHHs)." (PMID 37094077, 2023). "Despite the fact that IFN and IRF1 pathways have long been considered to be highly effective at resisting and controlling pathogen infections, their common target PLAAT4 has not been recognized as a restriction factor for any pathogen until recently." (PMID 37063830, 2023). "Seemingly paradoxically, PLAAT4 as an effector of IRF1/IFNs does not affect or depend on the canonical innate immune signaling; rather, it directly restricts pathogen infections via the acyltransferase activity in both cases." (PMID 37063830, 2023).
neurodegenerative disease (1 paper, 2023). A disorder of the central nervous system characterized by gradual and progressive loss of neural tissue and neurologic function. "The GSEA results demonstrated that these 3 key genes (DLD, PLPP2, and PLAAT4) were all associated with neurodegenerative diseases, which supports the notion that the identification of these key genes was accurate to some extent." (PMID 37736681, 2023).
PLAAT4 also shares sentences with these, for which no sentence is quoted: melanoma (6 papers); colorectal cancer (5); bladder cancer (3); liver cancer (3); viral infection (3); B-cell lymphocytic leukaemia (2); colon carcinoma (2); cutaneous melanoma (2); gastric cancer (2); lung adenocarcinoma (2); skin cancer (2); adenocarcinoma (1); adenoma (1); adenovirus infection (1); alcohol dependence (1); Alzheimer disease (1); Autoimmunity (1); colon adenocarcinoma (1); colorectal adenocarcinoma (1); colorectal tumours (1); dermatomyositis (1); follicular thyroid carcinoma (1); glioma (1); head and neck squamous cell carcinoma (1); hematological diseases (1); Hip dysplasia (1); Huntington disease (1); lung (1); metastatic disease (1); mucinous adenocarcinoma (1).
A further 12 diseases each share a sentence with PLAAT4 in 1 paper.